IL6 (interleukin 6)
Diseases named in the same sentence as IL6 in open-access papers (continued):
Sharing a sentence is not in itself a finding about the gene and the disease.
depression (continued). "Indeed, proinflammatory cytokines, including IL-1beta, interleukin-6 (IL-6), and tumor necrosis factor-alpha (TNF-alpha), have been implicated in the etiology of depression, contributing to cellular damage, impaired neuronal plasticity, and neurotransmission in the prefrontal cortex and hippocampus." (PMID 35237160, 2022). "Thus, possible associations between depression subtypes and its pathogenic characteristics with controls may be drawn through plasma levels of C-reactive protein (CRP), IL-6, IL-10, and leukocyte subpopulation in blood composition." (PMID 36217471, 2022). "Therefore, IL-6 is identified as a novel target for major depressive disorder treatment." (PMID 35267944, 2022). "However, our study demonstrated an association between IL-6 levels and psychosomatic syndromes while there was no such association with depression." (PMID 35271674, 2022). "The elevated expression of the inflammatory cytokines IL-2 and IL-6 in the intestine and brain tissues of patients with post-stroke depression decreased following exercise intervention, which may be related to the enhanced expression of Lactobacillus and Bifidobacteria." (PMID 36389714, 2022). "A recent longitudinal study also demonstrated that higher weight predicted more severe depressive symptoms and worse EF via higher levels of IL-6, and depressive symptoms also predicted IL-6 increase, and all observed associations were unique to depression but not anxious." (PMID 35534893, 2022). "Therefore, pro-inflammatory cytokines, including IL-1, IL-6, and TNF-α, may cause 5-HT synthesis deficiency by activation of the tryptophan metabolizing enzyme IDO, and finally lead to depression." (PMID 36686689, 2022). "Therefore, we can assume that IL-6 plays a role in anxiety and depression." (PMID 36034871, 2022). "In addition, IL-6 caused an increase in glucocorticoids and the activation of tryptophan 2, 3-dioxygenaes (TDO); this resulted in lower levels of serotonin (5-HT) in the brain, which has been confirmed to be closely correlated with depression." (PMID 35757220, 2022). "Chronic inflammation may induce the development of atherosclerosis and arterial thrombosis, and elevation in inflammatory biomarkers (i.e., IL-6 and C-reactive protein) has been reported in various psychiatric disorders including post-traumatic stress disorder and major depression." (PMID 36269046, 2022). "Thus, IL-6 could participate in the morphological changes observed in the prefrontal cortex of individuals with an early stage of major depressive disorder." (PMID 36429454, 2022). "Treatment of RA with tocilizumab, an IL-6 antagonist, may reduce depression and anxiety ratings." (PMID 35330475, 2022). "IL-6 is a multifunctional pro-inflammatory cytokine that stimulates the inflammatory and auto-immune processes in many diseases including systemic inflammatory diseases such as rheumatoid arthritis and systemic lupus erythematosus, but also psychiatric diseases such as depression and chronic pain." (PMID 35628904, 2022). "Furthermore, it may be expected to exert prevention and treatment of disorders related to peripheral IL-6, including depression." (PMID 35267944, 2022). "Moreover, Probio-M8 treatment was more conducive to alleviating depression and anxiety in patients (P < 0.0001 versus the placebo group, day 180), with significantly lower serum levels of interleukin-6 and low-density lipoprotein cholesterol (P < 0.005 and P < 0.001, respectively)." (PMID 35343796, 2022). "Depression was identified during follow-up of other chikungunya outbreaks, and the idea of a possible mechanistic link between arthritis and depression was suggested following evidence of IL6 elevation in patients with chronic rheumatic symptoms after CHIKV infection." (PMID 36145421, 2022).
depression (continued). "While IL-10 is studied less frequently than IL-6, others illustrate that IL-10 concentrations are also increased in patients with depression, compared to healthy controls and similar to IL-6, they may be confounded by underlying inflammation and/or stress disorders." (PMID 34765010, 2021). "However, the meta-analysis of longitudinal studies showed that the increased level of IL-6 may precede the development of depression and is elevated in people with clinical symptoms, although not always unequivocally." (PMID 34945157, 2021). "Evidence from Mendelian randomization (MR) studies, which use genetic variants regulating levels/activity of a biomarker as proxies to address the issue of confounding, suggest that IL-6 and CRP could be potentially causally related to depression and psychosis." (PMID 33684738, 2021). "Elevated levels of IL-6 have been demonstrated in people under stress in laboratory conditions, those diagnosed with depression, as well as in people diagnosed with seasonal affective disorders and among elderly people suffering from depression as well as among women in puerperium." (PMID 34945157, 2021). "In a study that followed adolescent females at higher risk of depression for more than 2.5 years study, adolescents with a history of early life stress had greater increases in IL-6 and CRP when they became depressed than their peers without a history of early life stress." (PMID 34890365, 2021). "Additionally, IL-6 and TNF-α negatively impact serotonin production and integrity, which may increase the risk of depression." (PMID 34576215, 2021). "The lack of association between depression symptoms and IL-6 or CRP in our cohort as compared to other cohorts may reflect differences in the distribution of age, sex, or body composition between the cohorts." (PMID 32691611, 2021). "Interestingly, elevated IL-6 levels are observed in COPD as well as in depression itself." (PMID 33669130, 2021). "Additionally, inflammatory cytokines may play an important role, such as interleukin-6 (IL-6), which was also elevated in individuals with CF or those with moderate to severe depression." (PMID 35153714, 2021). "IL-6 also affects the metabolism of oncological patients by induction of cancer cachexia and afflicts the central nervous system, where it may induce anorexia and depression." (PMID 34681685, 2021). "For example, changes in IL-6 serum levels have been reported as one of the most reproducible abnormalities in MDD, but some studies support the involvement of IL-6 in the pathophysiology of pediatric depression, and others do not." (PMID 34576215, 2021). "Moreover, IL-6 levels correlate differently among different depression subtypes, symptomology, and may be confounded by chronic inflammatory conditions that are often comorbid with ischemic stroke." (PMID 34765010, 2021). "Furthermore, higher levels of baseline IL-6 predicted depression chronicity over time." (PMID 32858844, 2020). "Furthermore, previous studies have shown that ketamine could alleviate LPS-induced depression-like behaviors, which were related to increased expressions of IL-1β and IL-6 and decreased expression of IL-10 in the rats." (PMID 32522211, 2020). "Besides, increased IL-6 serum level may act as a key factor in the onset of neuropsychiatric symptoms, including depression like phenotypes." (PMID 32010477, 2020). "Increased IL-6 could be an early marker for cognitive decline in depression." (PMID 33255237, 2020). "CRP is produced by hepatocytes under the regulatory control of IL-6 and other inflammatory cytokines, and these pro-inflammatory cytokines cause sickness behaviors, such as weakness, depression, exaggerated pain (hyperalgesia or allodynia), and lack of appetite." (PMID 33054839, 2020).
depression (continued). "In line with our expectations, the levels of the pro-inflammatory cytokines TNF-α, IL-1β, and IL-6 were decreased after the ketamine infusions in our study, which is consistent with the results of previous studies that administered a single infusion in patients with depression." (PMID 32699226, 2020). "In a mouse model of depression induced by a strong pathogen lipopolysaccharide (LPS), the expression of Toll-like receptor 2 in microglia was evidently increased, while RNA levels of neuroinflammatory factors, such as IL-1β and IL-6, in the cortex and hippocampus were significantly enhanced." (PMID 33192466, 2020). "Moreover, in a repeated social defeat stress (RSDS) mouse model of depression, it was reported that mice show individual differences in IL-6 production in response to RSDS, and that this intrinsic immune characteristic predicts susceptibility versus resilience to RSDS." (PMID 32518327, 2020). "There were no longitudinal associations between DGIH/BMI and depression, and adjustment for IL-6 and C-reactive protein did not attenuate associations between IR/BMI and depression; however, the longitudinal analyses may have been underpowered." (PMID 30854996, 2020). "Hence, it was hypothesized that stress-induced depressive disorder is likely to contribute to imbalance of glucose metabolism, and that cytokine IL-6-mediated disruption of glucose homeostasis signaling may participate in the process." (PMID 32655424, 2020). "The important role of neuroinflammation in MDD pathogenesis has created a new perspective that the combining of blood IL-6 and other depression-related cytokine levels may help to classify MDD biological subtypes, which may allow physicians to identify the optimal treatment for MDD patients." (PMID 32235786, 2020). "Moreover, elevated CRP and IL-6 were found significantly more frequently in individuals with rMDD than in healthy controls, and depression was associated with higher CRP levels, especially in the case of cumulative episodes of depression." (PMID 30995920, 2019). "Moreover, in addition to adversely affecting the gut microbiota, chemotherapy-induced mucositis is also associated with significant elevations in systemic pro-inflammatory cytokines, especially IL-1ß and IL-6, which are accompanied by increased symptoms of pain, anxiety, and depression." (PMID 31870331, 2019). "Plasma levels of IL-6 are known to be increased in patients with stable COPD compared to controls, remain elevated for a period, and may contribute to the increased risk of depression and mortality associated with COPD." (PMID 31612365, 2019). "Recently, this IL-6 SNP has been found to influence antidepressant treatment outcomes in major depressive patients, which might suggest a role for IL-6 in treatment resistant depression." (PMID 30967802, 2019). "It has also been shown that ketamine has anti-inflammatory properties that might contribute to its antidepressant effects, e.g., in patients with treatment resistant depression, serum IL6 concentrations were decreased only in patients who responded to ketamine therapy." (PMID 31827434, 2019). "Furthermore, inflammatory cytokines, particularly IL-6, may be related to depression in CKD/ESRD patients, which by itself is a predictor of morbidity and mortality and may result in decreasing nutrient intake." (PMID 29456507, 2018). "Population-based longitudinal studies have reported that higher levels of IL-6 and CRP are associated with symptoms/diagnosis of depression, mania and psychosis subsequently in life, suggesting low-grade inflammation could be a cause for these illnesses, rather than simply being a consequence." (PMID 29544672, 2018). "The therapeutic effect of long-term PA on depression likely includes the optimization of neurotransmitter level and function, hormone regulation, muscle-derived protein (e.g., peroxisome proliferator-activated receptor C coactivator-1α [Pgc-1α] and IL-6), and neurotrophic factors." (PMID 30093853, 2018).
depression (continued). "Furthermore, an increase in IL-6 has been found in patients with depression, which might lead to poor HRQOL scores in COPD patients." (PMID 29854031, 2018). "For example, elevated levels of interleukin (IL) IL-1β, IL-6, tumor necrosis factor alpha (TNFα) and C-reactive protein (CRP), and of corticotrophin releasing hormone (CRH) and cortisol, have all been described in association with antenatal symptoms of depression." (PMID 30033161, 2018). "IL-6 antagonists developed for autoimmune disorders are currently tested in clinical trials for depression (see, for example, ClinicalTrials.gov identifier NCT02473289), and ISG15 inhibition has been proposed as an antiviral strategy and could be repurposed for psychiatric indications." (PMID 29040650, 2018). "Consistent with this hypothesis, a number of studies have found elevated peripheral cytokines (particularly tumour necrosis factor (TNF) and interleukin-6 (IL-6)) in depressed patients, and depression is the most observed psychiatric comorbidity of medical illness." (PMID 28176274, 2018). "These associations included: higher IL-6 and IL-8 were associated with a higher incidence of depression at 6 months, TNF-a levels with depression at 12 months, IL-5/IL-8/IL-12/TBF with apathy at 12 months, TNF-a with disinhibition at 12 months, and sVCAM/sICAM/sFAS with depression at 6 months." (PMID 28740480, 2017). "Furthermore, ketamine could decrease serum levels of IL-1β and IL-6 in rats with depression-like phenotype compared with saline treatment (P < 0.05)." (PMID 28600519, 2017). "Furthermore, serum levels of IL-1β and IL-6 at baseline may predict ketamine’s antidepressant effects in pain-induced depression." (PMID 28600519, 2017). "Interestingly, higher serum levels of IL-1β and IL-6 may accout for ketamine’s antidepressant effect in the rat with depression-like phenotype after SNI." (PMID 28600519, 2017). "Intense cardiovascular exercise has been shown to elicit generalized fatigue and depression associated with changes in the expression of neurotransmitters such as glutamine, dopamine and 5-HTP and the production of large quantities of proinflammatory cytokines such as IL-1β, IL-6 and TNF- α." (PMID 28360847, 2017). "Furthermore, the authors found an OR of 3.18 for depression in patients with high IL-6 levels." (PMID 27918465, 2016). "Therefore, the changes in IL-6 levels observed in this study may suggest that COPD and depression as well as COPD with comorbid depression are associated with chronic inflammation." (PMID 26403459, 2016). "Thus, IL-6 and other cytokines may be more relevant in the development of somatic symptoms compared to affective signs of depression, delineating a specific genotype–phenotype relationship in this heterogeneous disorder." (PMID 26821321, 2016). "Self-esteem remained significantly associated with IL-6, CRP, and MMP-9 also after adjustment for hopelessness, vital exhaustion, or depression using dichotomy scale and with marginal significance for IL-6 (p = 0.06) and CRP (p = 0.061) after control for depression using continuous scale." (PMID 26979423, 2016). "In the Whitehall II study, for example, high levels of CRP and IL-6 at baseline have been associated with an increased risk of future cognitive symptoms of depression whereas baseline symptoms of depression did not predict the level of CRP or IL-6 at follow-up." (PMID 26631274, 2016). "The fine tuning of IL-6 expression is crucial since dysregulation of IL-6 has been attributed to many diseases such as atherosclerosis, systemic lupus erythematosus, Behçet′s disease, diabetes, multiple myeloma, depression, Alzheimer′s Disease, prostate cancer and rheumatoid arthritis." (PMID 25762865, 2015). "Particularly elevated IL-6 may play a key role in the development of depression." (PMID 26300773, 2015).
depression (continued). "However, it seems that HPA axis and sympathetic nervous system activity, as well as that of circulating IL-1β and IL-6, may vary greatly in individuals with typical vs. atypical features of major depression." (PMID 25565946, 2014). "This implies that different cytokines are involved in both depression and sickness behaviors, and that IL-6 may contribute to the pathogenesis of depression, though further studies are needed to reveal individual mechanisms pertaining to each respective behavioral pattern." (PMID 25309465, 2014). "Elevation of IL-6 concentration may increase symptoms of depression." (PMID 25275647, 2014). "Thus, stress via enhanced release of pro-inflammatory cytokines such as TNF-α, IL-1β and IL-6 may not only precipitate depression, but may also accelerate the neurodegenerative processes." (PMID 25514226, 2014). "In addition, vascular risk factors, including high body mass index level, presence of inflammation markers (e.g., CRP, TNF-α, Hs-CRP, and IL-6), and lack of physical activity, were associated with depression." (PMID 24752391, 2014). "However, similar designs have been used in many studiesdemonstrating associations between depression and inflammation, and previously wehave shown that CRP, IL6 and measures of adiposity in our sample are positivelyassociated in ways that are consistent with prior research." (PMID 24481182, 2013). "Therefore, the mechanism that links the therapeutic effect of light in depression may be the immune system, specifically by IL-6." (PMID 23497121, 2013). "Elevated IL-6 in depression may be particularly relevant to cognitive symptoms." (PMID 24481186, 2013). "Interestingly, present data also demonstrated that the level of IL-6 and TNF-á was positively correlated with the depressive behavior, supporting the hypothesis that the inflammatory cytokines cause development of depression." (PMID 22860054, 2012). "Moreover, a clinical control group with a psychiatric disorder such as depression or psychosis/schizophrenia might add knowledge on the dual role of the IL-6 gene in health and disease states." (PMID 22695063, 2012). "Associations between circulating IL-6 levels and negative mood have been reported previously and IL-6 frequently has been discussed as a potential modulator of mood during sickness behavior and even depression and other neuropsychological diseases." (PMID 22164271, 2011). "Disease symptoms include lethargy, depression, failure to concentrate, anorexia, sleep disturbances, reduction in personal hygiene or social withdrawal, and are mediated by proinflammatory cytokines, such as interleukin-1 (IL-1), interleukin-6 (IL-6) and tumor necrosis factor α (TNFα)." (PMID 21831269, 2011). "LLE improved CRS-induced anxiety- and depression-like behaviors, reduced microglial activation in the hippocampus, and suppressed TLR4/MyD88/NF-κB signaling and downstream cytokine release (TNF-α, IL-6, IL-1β)." (PMID 42255668, 2026). "Interleukin-6 (IL-6) and C-Reactive Protein (CRP) with depression were the primarily assessed inflammatory and mental health outcomes." (PMID 42031703, 2026). "The results showed that the mRNA levels of IL‐1β, iNOS, IL‐6, and TNF‐α were increased in the brain of depression model mice, and all of them were down‐regulated in the DSCG‐treated depression model mice." (PMID 41556446, 2026). "Large meta-analyses of peripheral blood markers have shown elevated levels of CRP, IL-6, TNF-α and other cytokines in patients with depression compared with controls, with substantial heterogeneity suggesting an “inflamed” subgroup." (PMID 41561481, 2026). "Our study found that participants with severe depressive symptoms had significantly higher concentrations of CRP, IL-6, and TNF-α, reaffirming a robust link between inflammation and depression." (PMID 40363978, 2025).